CHEK2 (checkpoint kinase 2)
Diseases named in the same sentence as CHEK2 in open-access papers (continued):
Sharing a sentence is not in itself a finding about the gene and the disease.
cancer (continued). "One patient (Epi132) revealed family cancer occurrence resembling families harboring CHEK2 mutations in general, the other patient (epi203) was non-conclusive." (PMID 18725978, 2008). "In addition, the lack of significant difference between case and control participants in all-cause mortality in individuals with cancer suggests that germline CHEK2-associated cancer was not clinically more aggressive than non–CHEK2-associated cancer." (PMID 41396600, 2025). "Given that CHEK2 is primarily associated with malignancies typically presenting in adulthood, prior findings emphasize the importance of long‐term post‐HSCT surveillance to assess the potential impact of CHEK2 variants on late‐onset complications and secondary cancer development." (PMID 40506802, 2025). "This pattern suggests that statins may partially inhibit cancer DNA repair mechanisms by altering the normal phosphorylation dynamics of key kinases such as CHEK2 and ATM (which also decreases their phosphorylation), thereby weakening the cellular response to DNA damage." (PMID 40832614, 2025). "Furthermore, the TMB was not significantly different between breast and non-breast CHEK2-deficient cancers (P = .2786)." (PMID 38848470, 2024). "Interestingly, the CHEK2 I157T variant is not reported on standard germline inherited cancer panels in most countries outside of the United States, specifically because it does not reach the risk threshold to independently guide care." (PMID 39062660, 2024). "In addition, the lack of significant difference between CHEK2 All heterozygotes and controls in all-cause mortality in individuals with cancer suggests that germline CHEK2-associated cancer is not clinically more aggressive than non-CHEK2-associated cancer." (PMID 39371170, 2024). "Genetic and pharmacological inhibition of CHEK2 in lymphoid and myeloid cell lines reduced PARPi-induced hematologic toxicity, further demonstrating that specific CHEK2 inhibition may be used to alleviate cancer treatment–induced toxicities." (PMID 37862420, 2023). "Furthermore, the study suggests that the model is well-calibrated for moderate penetrance genes such as CHEK2 and ATM, which may have implications for the validity of cancer risk predictions." (PMID 37237042, 2023). "When homologous recombination repair genes BRCA1/2, ATM, PALB2, and CHEK2 are inactive, a variety of error-prone and non-conservative DNA repair pathways are used, increasing the incidence of cancer and worsening its prognosis while also causing genomic instability." (PMID 37732318, 2023). "Eight targets (EP300, CASP3, CASP8, CHEK2, CREBBP, NOTCH1, PPARG, and TGFBR2) were TSGs (gray text), suggesting that antagonizing these molecules might increase the susceptibility to cancer in healthy individuals." (PMID 37888486, 2023). "Furthermore, one of our patients carried a known pathogenic CHEK2 c.1100delC mutation, despite having no family history of cancer." (PMID 34011307, 2021). "Nonsense mutations that are predicted to be pathogenic and cancer-related in ClinVar are in RB1 in UM-MCC9 (rs794727481) and UM-MCC34 (rs121913304), in BAP1 in UM-MCC32 (chr3.52437267.G > A), and in the tumor-suppressor gene CHEK2 in MKL-1 (chr22.29091725.C > T)." (PMID 33562873, 2021). "Therefore, CHEK2 is essential for cell cycle regulation, and its abnormal expression could lead to cancer." (PMID 34768979, 2021).
cancer (continued). "More specifically, Cybulski and colleagues estimated the lifetime BC risk for truncating CHEK2 mutations in Polish patients to be 20% in women without a family cancer history and 28% and 34% in women with a second- and first-degree relatives with BC, respectively." (PMID 33322746, 2020). "According to the correlation between CHEK2 and TP3 genes and the role of CHEK2 (suppressor gene that is involved in DNA repair, cell cycle arrest, or apoptosis in response to DNA damage)—mutations to the CHEK2 gene have been labeled as causes to a wide range of cancers." (PMID 32570972, 2020). "We then focused on the germline mutations in cancer-related functional genes and found a novel deleterious heterozygous nonsynonymous mutation (chr22:29091846, G->A, p.H371Y) in CHEK2, which is not recorded in the 1000 genome database and dbSNP137." (PMID 27442652, 2016). "Although it is unclear whether identifying a mutation in a moderate risk gene like CHEK2 will change the care for family members who have elevated empiric risks already, it may illuminate cancer risks that are not apparent based on the family history alone." (PMID 26484312, 2015). "Thus, CHEK2 could be a future target of cancer genetic test that could help in the detection and prevention of various cancers." (PMID 25431674, 2014). "With regard to the third criterion, some investigators have argued that in the context of a high-risk family, the difference in risk between carriers and noncarriers of clearly pathogenic CHEK2 sequence variants is sufficient to justify a difference in cancer surveillance strategies." (PMID 21244692, 2011). "Screening for CHEK2 mutations has not been well integrated into genetic counselling for cancer." (PMID 19401704, 2009). "Machine learning models based on seven LM-related genes (CHEK2, LIPT1, TUFM, NDUFA10, AGK, PNPLA2, and GFM1) accurately predicted immunotherapy outcomes for multiple cancer types, including LUSC, and outperformed other currently known biomarkers." (PMID 40568577, 2025). "The distribution patterns of several known cancer driver genes, including CTNNB1, ATM, CHEK2, and NCOR1, exhibit racial disparities across datasets." (PMID 39541191, 2024). "From the Cancer Genome Atlas (TCGA), we also retrieved the LST and tAI counts of cancers from individuals who are heterozygous for CHEK2 gPVs or BRCA1/2 gPVs." (PMID 38848470, 2024). "Hence, we could not compare all CHEK2 variants detected in the study cohort to a non-cancer Turkish population." (PMID 39594831, 2024). "In addition, germline mutations in CHEK2 have been found with a prevalence of 4% in patients with PanC, and a number of genetic alterations of the proofreading domain of DNA polymerases, such as POLE or POLD1, have been associated with the risk for human cancers." (PMID 36717774, 2023). "At the same time, in a large-scale study of BC women aged 35–59 years, who were mainly of Northern and Western European descent, PVs in CHEK2, ATM, PALB2, and PMS2 genes were the most frequent among the 25 cancer genes tested, after PVs in BRCA1/2." (PMID 37791908, 2023). "Of these, the most commonly seen are in the Breast Cancer gene 1 (BRCA1), Breast Cancer gene 2 (BRCA2), Checkpoint kinase 2 (CHEK2) and partner and localizer of the BRCA2 gene (PALB2) tumour suppressor genes." (PMID 36831687, 2023).
cancer (continued). "E2F1 and CHEK2 were highly expressed across most cancer types compared to normal samples, while PDK4 and NTRK2 were decreased in various cancers." (PMID 36937870, 2023). "The most common genes in which PPGVs were identified pan-cancer were BRCA2 (16.9% of PPGVs), MUTYH (15.0%), ATM (13.4%), CHEK2 (11.7%), and BRCA1 (9.8%)." (PMID 37568048, 2023). "Among the ligands, this compound (1,2-benzenedicarboxylic acid) exhibited the highest binding affinity, particularly with crucial cancer-related genes, including MET, EPCAM, PTEN, and CHEK2." (PMID 38116103, 2023). "Among 10,480 cancer patients, we identified 20 individuals with HCC diagnosis of which two were PV carriers in established CPGs (BRCA1 and CHEK2)." (PMID 36612198, 2022). "FOXK2 is phosphorylated at Ser61 by checkpoint kinase 2 in the context of DNA damage; this traps FOXK2 in the cytoplasm, resulting in inhibition of apoptosis in cancer cells." (PMID 34866322, 2022). "Overall, the six genes that had PVs with prevalences greater than one percent for any patient cohort (ATM, BRCA1, BRCA2, CHEK2, CDKN2A and FANCA) comprise a heterogenous group of genes that reflect the complexity of this cancer." (PMID 34255164, 2021). "In this analysis, we only considered genes that were affected in at least four TCGA cases within a cancer type and therefore only seven genes (BRCA1/2, ATM, ATR, PALB2, CHEK2, BRIP1) were included." (PMID 34572800, 2021). "CHEK2 and CDKN2A are known tumor suppressors, and TMPRSS2 and ERG are frequently involved in translocation events forming fusion oncogenes in certain cancers." (PMID 30736820, 2019). "However, the uncomplicated co-segregation pattern seen in BRCA1 and BRCA2 families, where (almost) all BC patients carry the predisposing mutation and where mutation carriers have a high risk to develop cancer (typical for high penetrant monogenic diseases), is not found in CHEK2 families." (PMID 28649653, 2017). "Strikingly, both sample sets shared six genes in their ‘top 20’ list of most frequently lost ‘Cancer census genes’ (i.e. EP300, SETD2, PBRM1, CHEK2, MKL1 and MAPK1)." (PMID 29371938, 2017). "Six other ‘Cancer census genes’ however, were listed among the most frequently lost ones, both in the TCGA- and LP-WGS-dataset (i.e. EP300, SETD2, PBRM1, CHEK2, MKL1 and MAPK1)." (PMID 29371938, 2017). "The proband decided to undergo genetic testing with a comprehensive cancer panel, and the results identified a VUS in the CHEK2 gene." (PMID 29225998, 2016). "Top-ranking kinases such as AKT1, CHEK2, and ABL1 regulate core cellular processes of growth and proliferation, and are well-studied cancer drivers according to the CancerGenes database." (PMID 25611800, 2015). "Accordingly, this study identifies two evolutionarily conserved SL interactions, namely BLM SOD1 and CHEK2 SOD1, and defines SOD1 as a novel candidate drug target in cancers harboring BLM and CHEK2 defects." (PMID 26318585, 2015). "Nonetheless, several gene sets with potential importance for cancer development are enriched such as genes positively correlated with BRCA1, ATM, and CHEK2 expression across normal tissues (GSEA, q < 10-28)." (PMID 25768983, 2015).
cancer (continued). "However, bilateral cancer is not unusual in the multicase families recruited by kConFab, and the association between CHEK2 1100delC may be coincidental." (PMID 15700044, 2005). "During the study period, moderate cancer risk genes such as ATM, CHEK2, and BARD1 were not analyzed in Denmark." (PMID 40408052, 2025). "Genetic testing was negative for BRCA1/2, CHEK2, and PALB2 mutations, though familial cancer history suggested a possible hereditary syndrome (FCC suspicion)." (PMID 40926949, 2025). "Six of these PGVs were in cancer predisposition genes (ATR, CHEK2 (3x), SDHA and MITF) without an established association with familial glioblastoma." (PMID 41168197, 2025). "Nonetheless, these data provide a rationale for the lack of efficacy of PARPi in CHEK2-mutant cancers given the lack of apparent HRD." (PMID 38950525, 2024). "In contrast to the CHEK2-deficient cancers, BRCA1/2-deficient cancers did not present with mutational signature SBS1 (0/28 cancers; 0%; P < .05), and a minority presented with mutational signature SBS5 (11/28 cancers; 39%; P < .05)." (PMID 38848470, 2024). "Interestingly, CHEK2-related DFSP cases in this study often occurred in the third decade of life, which is considerably younger than the mean age at diagnosis for this cancer in Geisinger and UK Biobank." (PMID 39669616, 2024). "CHEK2 rMSVs are also associated with smaller risks of a similar range of cancers; for ATM (but not CHEK2), the risks appear to be restricted to a small subset of rMSVs." (PMID 39209703, 2024). "In addition to BRCA1 and BRCA2, many other HRR mediators (ATM, BRIP1, CHEK2, NBS1 or RAD51C) are frequently defective in cancer." (PMID 37298484, 2023). "The ABL1-I418T, PIK3CB-R231H, CHEK2:c.-4C > T, BRCA2-P3292L, ABL1-E459G, PRPF8-G1796R, PHF6-R274Q, WT1-R435X and ATM-C117Y variants were potentially important cancer variants which were not actionable." (PMID 35896598, 2022). "In our series, just one of the patients with a GPV in CHEK2 had a contralateral BC and none of the patients with a GPV in the moderate-risk BC genes had other primary cancers (excluding BC)." (PMID 36119527, 2022). "Our studies show that CHEK2 is a critical SF3B1 target, as ectopic expression of CHEK2 demonstrates high synergy of SF3B1 inhibitors with CHEK2 inhibitors as well as chemotherapeutic drugs, and propose that the SF3B1 inhibitor E7107 is a lead compound that sensitizes cancer cells to chemotherapy." (PMID 35061527, 2022). "A recent systematic review identified ATM, BRCA1, BRCA2, CDKN2A, CHEK2, and PALB2 as the most frequent genes harboring GPV in individuals with PDAC not meeting criteria for any cancer predisposition syndrome with varying degrees of family history." (PMID 35805029, 2022). "DDR genes including ATM, ATR, CHEK2, POLE, and POLQ could serve as potential biomarkers of ICI response, but their distinct and cancer-specific effects need to be investigated further." (PMID 34095878, 2021). "Besides, PAK1 phosphorylates Raf at S338 to activate checkpoint kinase 2 (CHK2), leading to DNA damage response and cancer cell survival." (PMID 33796531, 2021). "Other critical components of the DDR, including ataxia telangiectasia and Rad3-related (ATR), ataxia telangiectasia mutated (ATM), DNA-dependent protein kinase (DNA-PK), Checkpoint kinase 1 (CHK1), Checkpoint kinase 2 (CHK2) and Wee1 kinase (WEE1), are also promising as targets for fighting cancer." (PMID 34885119, 2021).
cancer (continued). "Conclusions from each of the described case studies of co-existing CHEK2 and BRCA variants suggest no significant increased cancer risk or difference in phenotype beyond what is expected with a single BRCA variant." (PMID 33507482, 2021). "While the CI for biallelic CHEK2 PV carriers are wide for both ductal invasive breast cancer and DCIS, the lower end of the CI range for both show at least a twofold higher risk of cancer compared to non-carriers." (PMID 31993860, 2020). "Only 9.7% (3/31) of biallelic CHEK2 PV carriers were reported with no history of cancer, compared to 50.0% (3234/6473) of monoallelic CHEK2 PV carriers." (PMID 31993860, 2020). "Other well-known cancer genes such as BRCA1, CHEK2, JUN, and MYC could also be found in the highly interconnected regions of the PPI network." (PMID 29540752, 2018). "However, the presence of pathogenic variants in CHEK2 is not frequently associated with cancer in high-risk BC families, prompting speculation that there may be several low-penetrance or moderate-penetrance BC risk genes segregating independently within these families." (PMID 29458332, 2018). "Most cancers in non-carriers or in CHEK2 carriers are ER-positive whereas cancers in BRCA1 carriers are usually triple-negative and these are relatively aggressive in their natural history." (PMID 28265306, 2017). "To determine whether MSH3 is involved in DNA DSB repair, we determined the effect of anti-cancer drug treatment upon expression of the DSBs markers, phosphorylated histone H2AX (pH2AX) and Checkpoint kinase 2 (pChk2)." (PMID 23724141, 2013). "All BC c.1009-118_1009-87delinsC variant carriers with known histology (18/21) developed ER-positive primary tumors, six developed double-primary cancers, and only two with known family cancer history (18/21) had negative or CHEK2-irrelevant family cancer history." (PMID 38554551, 2024). "All, except 2 cancers with a heterozygous CHEK2 gPV, did not harbor a somatic second hit." (PMID 38848470, 2024). "Additionally, we assessed the allele frequencies of the genes in the gnomAD non-cancer cohort (n = 134 187), which showed significant differences in BRCA1, BRCA2, CHEK2, MUTYH, MSH6, POLE, and ERCC3 genes in comparison to our non-HBOC groups." (PMID 39148954, 2024). "For some families, knowledge of a CHEK2 alteration in an otherwise healthy child without any recommended cancer screening in childhood may lead to increased distress." (PMID 36980535, 2023). "Considering the potential use of CHEK2 inhibitors for primordial oocyte protection, more information is needed regarding CHEK2 activation and its downstream effectors in chemotherapy-induced POI to identify cancer treatments that could benefit from oocyte-protective activity of CHEK2 inhibitors." (PMID 37862420, 2023). "Therefore, inhibitors blocking CHEK2 and CHEK1 could have dual benefits for female patients: improved cancer cell elimination and oocyte protection." (PMID 37862420, 2023). "However, CHEK2 has been excluded as a major LFS gene, but rather represents a moderate risk gene for individual cancer susceptibility within LFS clusters." (PMID 36387164, 2022). "While loss of function CHEK2 mutations might contribute to increased risks of individual cancer development in LFS/LFL families, several studies have ruled out CHEK2 as a major LFS/LFL susceptibility gene." (PMID 36387164, 2022).